DLC1 (DLC1 Rho GTPase activating protein)
Diseases named in the same sentence as DLC1 in open-access papers (continued):
Sharing a sentence is not in itself a finding about the gene and the disease.
cancer (continued). "DLC1—a Ras homolog GTPase-activating protein (RhoGAP) that negatively regulates the activity of RhoA-C and is a potent tumour suppressor whose loss has been implicated with numerous cancers —is a notably interesting talin-binding partner." (PMID 30028837, 2018). "In addition to deletion of DLC1, reduced expression of DLC1 in cancer has also been linked to promoter hypermethylation." (PMID 27174913, 2016). "In some cancers, the loss of DLC1 expression was shown to be of prognostic value." (PMID 27614886, 2016). "This study provides new evidences that tumor suppressor gene DLC1, through its RhoGAP activity, affects the activation of NF-κB and, thus, modulates the complex signal transduction pathways, which associate with inflammatory response and cancer progression." (PMID 24683532, 2014). "The results obtained so far indicate that MKL1/2 may be valuable targets for the therapy of DLC1-deficient cancers." (PMID 23853104, 2013). "Since the MKL/SRF signalling axis is of critical importance to cancerous transformation upon DLC1 loss, MKL1/2 might represent a promising pharmacological target for the therapy of DLC1-deficient cancers." (PMID 23853104, 2013). "Underexpression of DLC1 is also implicated in other cancers such as breast, lung, and prostate." (PMID 18648664, 2008). "From examinations of several cancers, point mutations leading to the inactivation of DLC1 are rare." (PMID 17519008, 2007). "In recent years, the therapeutic potential of restoring DLC1 expression by inhibiting its proteasomal degradation across various cancer types has gained increased attention." (PMID 41317652, 2026). "Enhancer of zeste homolog 2 (EZH2) is a frequently upregulated epigenetic factor in human cancers, while deleted in liver cancer 1 (DLC1) is an anticancer gene that is often expressed at low levels or not expressed in many malignancies." (PMID 40989587, 2025). "Experimental results confirmed that DLC1 downregulation promotes the cadherin switch in mesenchymal cells upon TGFβ withdrawal, thus potentially providing an advantage to metastatic cancer cells during colonization of distant organs." (PMID 40354489, 2025). "Jointly, these observations provide a rationale for the development of targeted therapies that harness this protective function of DLC1 on intracellular tension in cancer." (PMID 38563084, 2024). "In cancer, p120RasGAP inhibits the RhoGAP activity of Deleted in liver cancer 1 (DLC1, i.e., STARD12, ARHGAP7), which is a tumor suppressor." (PMID 37958606, 2023). "This study uncovered a cytoskeleton-independent role of DLC1 in cancer metastasis, but it depended on RhoGAP function yet." (PMID 36185184, 2022). "We explored the prognostic relation between the expression of DLC1 and 33 different types of cancers, indicating the correlation between lower DLC1 expression and a poor UCEC prognosis." (PMID 35223504, 2022). "DLC1 is mapped to the chromosome 8p21-22 region that is deleted in various human cancers commonly and is assumed to harbor tumor suppressor genes." (PMID 36185184, 2022). "For DLC1, which is known to function as a GTPase-activating protein for Rho family members, plays an important role in cancer development and progression." (PMID 36173625, 2022). "We employed the TCGA database to assess how DLC1 expression was related to prognosis by analyzing 33 TCGA cancer types." (PMID 35223504, 2022). "Meanwhile, as an emerging metastasis suppressor gene, DLC1 can inhibit cancer progression and oncogenic autophagy in HCC." (PMID 33591950, 2021). "EZH2 is an oncogenic factor commonly upregulated in human cancers, while DLC1 is a downregulated tumor suppressor in many malignant tumors." (PMID 34680593, 2021). "On the other hand, the relative expression level of DLC1 in cancer tissues was found to be significantly downregulated, by 0.4-fold compared to the normal tissues (p < 0.0001)." (PMID 34071861, 2021).
cancer (continued). "Several RhoGAPs, such as DLC1 and DLC2, are downregulated in various human cancers, but only p190A has been identified as a significantly mutated gene in human cancers." (PMID 32457342, 2020). "This is in sharp contrast to previous findings in other cancer types, in which DLC1 KD promoted cell proliferation, tumor formation, and invasion, while DLC1 OE reversed these phenotypes." (PMID 32214200, 2020). "Here, we undertook a pan-cancer analysis and identified residues within DLC-1 and DLC-2 START domains likely to affect the function of these genes." (PMID 33142932, 2020). "The results showed that EZH2 and DLC1 were differentially expressed in patients of different ages, races, cancer stages, molecular subtypes and histologic subtypes." (PMID 32725802, 2020). "The deleted in liver cancer 1 (DLC-1 or STARD12), DLC-2 (STARD13), and DLC-3 (STARD8) RhoGAPs are frequently down-regulated in cancer and associated with poor prognosis." (PMID 33142932, 2020). "Deleted in liver cancer 1 (DLC1) is tumor suppressor gene that codes for a RhoGTPase activating protein inactivated in many types of cancer." (PMID 30415495, 2019). "This is an attractive model not just in light of the results presented but also when considered with respect to the role of DLC1 deletion in cancers." (PMID 30028837, 2018). "The role of highly activated and contractile cells in the cancer progression has been investigated before, and it is possible that DLC1’s role in cancer (by its absence) is mediated through the subsequent lack of control over focal adhesion activation." (PMID 30028837, 2018). "Acetylation of K-Ras, phosphorylation and acetylation of FoxOs, and phosphorylation of DLC1 have been reported to have dual effects on proliferation and apoptosis in cancer cell lines, orthotopic cancers of nude mice or transgenic mice." (PMID 28903430, 2017). "Expression of different alternative DLC1 transcripts was considered only in a very few cancer studies." (PMID 27614886, 2016). "This includes the promoter of DLC1-v2 that was reported as being hypermethylated in diverse cancers." (PMID 27614886, 2016). "DLC1 expression was higher in TCGA LAD patients who remained cancer-free, while low DLC1 had a poorer prognosis than low DLC2 or low DLC3 in a more completely annotated database." (PMID 27174913, 2016). "In another study, frequent epigenetic downregulation of DLC1-v5 was identified in certain human cancers and a panel of different cell lines." (PMID 27614886, 2016). "We conclude that in several cancers DLC1 is the principal biologically-relevant down-regulated DLC family member, although down-regulation of DLC2 and DLC3 is also observed." (PMID 27174913, 2016). "This conclusion, which parallels the physiologic observation that DLC1 is essential for fetal development, while DLC2 and DLC3 are dispensable, implies that analyses of the DLC genes in cancer analyses should focus preferentially on DLC1." (PMID 27174913, 2016). "The results showed that transfection of miRNA483-3p antagomir induce expression of DLC-1 and inhibit cancer cell growth, further verifying the oncofunction of miR-483-3p." (PMID 27366946, 2016). "We conclude that DLC1 is the predominant family member expressed in several normal tissues, and its expression is preferentially reduced in common cancers at these sites." (PMID 27174913, 2016). "A subsequent study based on the comparative hybridization technique demonstrated that the chromosomal region spanning DLC1 (8p21) shows frequent deletions in various types of cancer." (PMID 25013499, 2014). "Ullmannova and Popescu first reported the downregulation of DLC-1 mRNA expression in CRCs utilizing cancer-profiling arrays." (PMID 23509688, 2013).
cancer (continued). "Activity of Rho GTPases is elevated in many human cancers and their metastases, and the oncosuppressive effect of DLC1 requires RhoGAP activity, which negatively regulates Rho GTPases, most commonly RhoA." (PMID 23607551, 2013). "Indeed, our findings that DLC1 is a PcG-regulated target and its subsequent epigenetic silencing during malignancy progression are also in line with the recently proposed model on PcG marking of genes in ES cells are predisposed to de novo cancer specific DNA methylation." (PMID 23826380, 2013). "During malignancy development, the DLC1/Rho pathway is of particular importance owing to its regulation on the actin cytoskeleton related to cancer metastasis." (PMID 23826380, 2013). "DLC-1 is recurrently downregulated or inactivated by epigenetic mechanisms in the initiation and progression of cancers." (PMID 23509688, 2013). "Collectively, our findings suggest that epigenetic silencing of DLC1 is involved in the pro-metastatic function of EZH2 in human cancers." (PMID 23826380, 2013). "Inactivation of DLC1 results in hyper-activated Rho/ROCK signaling and is implicated in actin cytoskeleton reorganization to promote cancer metastasis." (PMID 23826380, 2013). "We further showed inactivation of EZH2 by 3-Deazaneplanocin A (DZNep) that re-expressed DLC1 and remarkably abolished cytoskeletal reorganization and inhibited cell migration in cancer cells." (PMID 23826380, 2013). "Three of four colon (75%) carcinoma cell lines were methylated in the DLC-1 promoter region at various levels (SW480: 76.9%, LoVo: 62.5%, and LS174T: 44%), whereas no CpG site was methylated in COLO 320 cells." (PMID 23509688, 2013). "Downregulation or inactivation of the DLC1 gene in many forms of cancer, is commonly mediated at the genomic level by heterozygous and homozygous deletion, and at the transcriptional level by aberrant promoter methylation or histone deacetylation." (PMID 22580498, 2012). "Among all cancer-related genes on chromosome 8, DLC1 and MYC play a major role in hepatocarcinogenesis, and evidence for their involvement in the development of HCC is presented next." (PMID 22580498, 2012). "DLC1 is also a contributing factor in processes affecting normal functions, or disorders unrelated to cancer." (PMID 22580498, 2012). "Downregulation or inactivation of TSGs has profound consequences in the genesis and progression of cancer, and DLC1 is one of the most frequently deregulated genes in the cancer genome." (PMID 22580498, 2012). "Other agents, such as all-trans retinoic acid and peroxisome proliferator-activated receptor γ (PPARγ), significantly elevated DLC1 expression in cancer cells." (PMID 22580498, 2012). "Accumulating evidence in the last decade has supported that DLC1 is underexpressed in various kinds of human cancers besides HCC." (PMID 21966542, 2011). "Deleted in liver cancer 1 (DLC1) serves as an important RhoGTPase activating protein (RhoGAP) protein that terminates active RhoA signaling in human cancers." (PMID 21966542, 2011). "By acting on various downstream molecules, DLC1 controls cell growth and migration in different kinds of cancers." (PMID 22272086, 2011). "Initial studies towards understanding the function of DLC1 were based on overexpression of the protein in different carcinoma cell lines, demonstrating inhibition of cell proliferation, migration and invasion." (PMID 20799942, 2010). "To demonstrate that some TSGs that are frequently hypermethylated in cancer and hESCs can lose methylation during differentiation, we focused our attention on DLC1." (PMID 18820729, 2008). "Moreover, while MRTF–SRF signalling has been shown to suppress oncogene-induced senescence and ERK activity in DLC1-deleted cancer cells, our Mrtfab−/− MEFs exhibited reduced ERK activity." (PMID 41200793, 2025).
cancer (continued). "Our study establishes an essential role of DLC1 in the dynamics of TGFβ-induced EMT and implies that cancer cells with DLC1 loss may be endowed with enhanced plasticity, favoring the survival of metastatic cells." (PMID 40354489, 2025). "Nevertheless, consistent with similarities in EMT, delamination, and cell migration between NCC and cancer cells, Dlc1 may also play an important role in promoting cell migration during cancer progression." (PMID 38873887, 2024). "The Rho GTPase activating protein Deleted in Liver Cancer 1 (DLC1) is frequently downregulated through genetic and epigenetic mechanisms in various malignancies, leading to aberrant Rho GTPase signaling and thus facilitating cancer progression." (PMID 35322810, 2022). "Considering that miR-186-5p is enriched in M2-EVs, we also tested whether M2-EVs could regulate DLC1 expression in cancer cells." (PMID 35280693, 2022). "DLC1 expression was significantly lower in the late stages than in the early stages of cancer." (PMID 35223504, 2022). "The Cancer Genome Atlas database was used for evaluating the expression of DLC1 in pan-cancer." (PMID 35223504, 2022). "The study next analyzed the correlation between DLC1 expression and cancer patient prognosis." (PMID 35223504, 2022). "The Rho GTPase-activating protein (RhoGAP), DLC1, has been well characterized as a tumor suppressor, as its expression was frequently found to be downregulated in various cancer types, and restoration of its expression in cancer cell lines inhibited tumorigenic growth." (PMID 32214200, 2020). "Notably, the RhoGAP DLC1, a tumor suppressor protein inactivating RhoA in many types of cancer, is phosphorylated by PKC/PKD protein kinases on Ser residues, which create binding sites for 14-3-3 proteins." (PMID 29545927, 2018). "An important issue not considered previously in most cancer studies on DLC1, is that multiple transcript variants of this gene have been identified." (PMID 27614886, 2016). "Similarly, our model identified genes that are frequently affected by aberrant methylation in other diseases such as cancer, including the tumor suppressors deleted in cancer 1 (DLC1) and transcription factor 21 (TCF21)." (PMID 24603652, 2014). "Collectively, the results from our study and previous work by others suggest epigenetic alterations of DLC-1 might occur as a consequence of overactivation of the oncogenic pathway in cancer." (PMID 23509688, 2013). "Furthermore, deletions of DLC1 occurred in other cancers more frequently than of some other well-known TSGs." (PMID 22580498, 2012). "To date, several new candidate cancer-susceptible genes have been cloned to 8p22, such as deleted in breast cancer 2 (DBC2), leucine zipper tumor suppressor 1 (LZTS1), deleted in liver cancer 1 (DLC1), and mitochondrial tumor suppressor 1 (MTUS1)." (PMID 22028972, 2012). "A number of compounds that restore DLC1 expression, extend the half-life of its protein, or mimic its function, in different cancers, also might be effective in therapy for HCC." (PMID 22580498, 2012). "We speculate nuclear mislocalization may be a potential mechanism in abrogating DLC1 activity in human cancer with intact DLC1 expression." (PMID 21966542, 2011). "We previously demonstrated that DLC1 is a RhoGAP protein and it is therefore logical to speculate that DLC1 suppresses cancer cell metastasis through negatively regulating ROCK-mediated cytoskeletal rearrangement." (PMID 18648664, 2008). "One of the important roles of DLC1 is its ability in repressing cancer cell migration and invasion." (PMID 18648664, 2008).
cancer (continued). "Besides, most of the cells expressed nuclear DLC1 in the control sections of pulmonary nodules, whereas a marked reduction in the number of nuclear DLC1-expressing cells were observed in sections of DLC1-depleted lung nodules, confirming the cellular origin of cancer." (PMID 32214200, 2020). "Finally, we found that transfection of miR-483-3p antagomir could induce the expression of DLC-1 and inhibit cancer cell growth." (PMID 27366946, 2016). "Thus, DLC-1 has the potential to be a key therapeutic indicator or markers for cancer gene therapy." (PMID 26846339, 2016). "Because epigenetic modifications are the main cause of DLC1 down-regulation and inactivation, therapy based on the ability of DNA methyl-transferase and histone deacetylase inhibitors (HDAC) to restore DLC1 expression in cancer cells has been highlighted as an attractive therapeutic approach." (PMID 22580498, 2012). "Although positive nuclear staining could be found in normal non-neoplastic liver in immunohistochemical staining, it would be interesting to observe whether there is a distinguishable difference of nuclear DLC1 staining between the normal liver tissue and DLC1-positive HCCs (or other cancer types)." (PMID 21966542, 2011). "Indeed, DLC1 silencing has been demonstrated to be a significant contributor to many human cancers." (PMID 19912643, 2009). "The analysis indicated that CXCR4, DLC1, and MAP1LC3C were significantly (FDR < 0.25, NP < 0.05) enriched in pathways related to immune response and cancer." (PMID 36173625, 2022). "This chromosomic region harbours the CSMD1, AGPAT5, TUSC3, DLC1, CLDN23, and MFHAS1 cancer-related genes." (PMID 30185896, 2018). "Some cancer-related genes are located in these highly common, early appearing RARs: MCL1, CTSK, ARNT, S100A10, PTK2, PTP4A3, and PSCA in the RAR-Gs; and DLC1, PINX1, and GATA4 in the RAR-Ls." (PMID 22938721, 2012). "Abnormal expression of DLC1 and p-FAK in many cancers suggests that they are involved in the malignant behavior of tumors." (PMID 22272086, 2011). "More recently, cten was considered to be a potential tumor suppressor by interacting with DLC-1 (deleted-in-liver-cancer-1), a member of RhoGTPase activating protein (GAP) family known to have suppressive activities in tumorigenicity and cancer metastasis." (PMID 21765928, 2011). "For several kinds of cancers, DLC1 down-regulation or deletion was reported to leave the Rho/ROCK/MLC pathway and RhoA GTPase pathway more active, resulting in the cancer cells’ endless proliferation and migration." (PMID 22272086, 2011). "Deleted in liver cancer 1 (DLC1), a member of RhoGTPase activating protein (GAP) family, is known to have suppressive activities in tumorigenicity and cancer metastasis." (PMID 18648664, 2008). "Several studies suggest that DLC1 and DLC2 are tumor suppressors involved in the progression of a wide range of cancers." (PMID 17519008, 2007). "It will be interesting to study the potential crosstalk of these degradation pathways in various cancer entities and also non-transformed cellular systems, to additionally understand their role in basal DLC1 turnover." (PMID 35322810, 2022). "The tumor suppressor gene DLC1 can be downregulated in cancers through genetic and non-genetic mechanisms." (PMID 34862367, 2021). "One limitation of this therapeutic approach is that it is only likely to benefit tumors with moderate to high levels of DLC1 protein, and DLC1 expression is frequently downregulated in a variety of cancers through genetic and non-genetic mechanisms." (PMID 34862367, 2021). "Among the identified genes, PRDM16 and DLC1 have been studied in various types of cancers, and the significance of these genes in OSCC has not been examined." (PMID 34051764, 2021). "Hepatocellular carcinoma deletion gene 1 (DLC1) is an antioncogene that is either expressed at low levels or not expressed in many malignant tumours." (PMID 32725802, 2020).